LNCATV (lncRNA negative regulator of antiviral signaling)
Gene: Long non-coding RNA gene on chromosome 1 (234,957,342 to 234,970,062, reverse strand). Ensembl gene ENSG00000238005.
Diseases named in the same sentence as LNCATV in open-access papers:
LNCATV is named in the same sentence as 2 diseases in open-access papers, as found by Europe PMC text mining. Sharing a sentence is not in itself a finding about the gene and the disease. The quoted sentences say what the papers report.
hepatoma (1 paper, 2019). "LncATV was cytoplasmic localized and relatively high expressed in human monocytes, erythroleukemia cells and hepatoma cells." (PMID 31379885, 2019).
virus infection (1 paper, 2019). "To further determine the functionality of lncATV in virus infection, we knocked down the endogenous lncATV using small interference RNAs (siRNAs) in Huh7 cells and the specific repression of lncATV expression by siRNAs was confirmed." (PMID 31379885, 2019).